BCL2 (BCL2 apoptosis regulator)
Diseases named in the same sentence as BCL2 in open-access papers (continued):
Sharing a sentence is not in itself a finding about the gene and the disease.
tumor (continued). "SLAMF7+ DNT exhibited significantly higher expression of the proliferation marker Ki67 and the anti-apoptotic marker BCL2, accompanied by a reduced apoptosis rate, confirming that SLAMF7 promotes DNT survival and tumor-infiltrating capacity." (PMID 41168829, 2025). "177Lu-PNP radiopharmaceuticaltherapy induced higherexpression of γH2AX, indicating that potent DNA damage occurred,and provoked the apoptotic pathways in the tumor, as evidenced bythe elevated BAX/BCL-2 ratio." (PMID 40442102, 2025). "The mixture of LHRHPEG-siRNA (BCL2)-MSN and LHRH-PEG-siRNA (MRP1)-MSN provided effective downregulation of BCL2 and MRP1 mRNA levels in vitro, leading to tumor regression." (PMID 40860190, 2025). "The results indicated a consistent decrease in BCL2 and BMP5 expression in most tumor samples, while PSMB8 and PSME2 showed increased expression." (PMID 41403941, 2025). "For example, IL-2 modified sEVs containing miRNAs against Bcl-2 and VEGF stimulated immune responses, tumor suppression and anticancer actions." (PMID 40688030, 2025). "For example, synthetic miR-34a mimics have shown potent anti-tumor activity in preclinical models: they inhibit epithelial–mesenchymal transition (EMT) and induce apoptosis by targeting BCL2 and MET, among other oncogenes." (PMID 41226828, 2025). "The combined use of apoptosis-regulating drugs, such as BCL-2 inhibitors, can lower the threshold for CAR-T cells to trigger tumor cell killing through pathways like death receptors." (PMID 40610404, 2025). "Cisplatin can inhibit the tumor cells apoptosis and produce drug resistance by regulating PI3K/AKT, Bax/Bcl-2 and other signal pathways." (PMID 40444086, 2025). "Therapeutic approaches that target apoptotic pathways, such as BCL-2 inhibitors that block survival signals and TRAIL analogues that trigger death receptors, aim to reinstate the apoptotic response in resistant tumor cells." (PMID 40420175, 2025). "This is also evident in other studies, where overexpressed IRF2 and downexpressed β-catenin led to decreased BCL2 levels in HCC samples, thus leading to better survival for tumor patients." (PMID 40456804, 2025). "Histopathological characterization and immunohistochemical staining, particularly CD34 in combination with Bcl‐2 and STAT6, are the basis for diagnosing this tumor." (PMID 41409894, 2025). "In PLC/PRF/5 tumor‐bearing mice and PDTX mouse models, ZAK‐I‐57 treatment (30 mg/kg) resulted in substantial downregulation of EGFR, c‐Myc, and Bcl‐2, with a concurrent increase in Bax expression." (PMID 40727254, 2025). "Sensitivity to a specific inhibitor (e.g., venetoclax or other BH3 mimetics) is then used to infer the reliance of a tumor (e.g., CLL) on one or more pro-survival BCL2 proteins." (PMID 40204951, 2025). "Immunohistochemical stains showed tumor cells positive for CD20, CD10, BCL-6, BCL-2, MUM-1, C-MYC, and with a high Ki-67 index (80%)." (PMID 39897193, 2025). "Immunohistochemical results showed that the tumor cells expressed Vimentin, SMA, Bcl-2, CD56, CD34, CD31, Ki-67, ERG, RB, INI-1, and SATB2, but were negative for SSTR2 and CK." (PMID 40406261, 2025). "As a selective antagonist of BCL-2, Venetoclax relieves the inhibition of Bax and Bak by competitively inhibiting the binding of BCL-2 to BIM, further leading to the apoptosis of tumor cells." (PMID 40525911, 2025). "Immunohistochemically, tumor cells showed patchy staining of CD34 and S100 protein, with weak focal staining for α- SMA, calponin, and Bcl-2." (PMID 40548109, 2025).
tumor (continued). "Thymol (75 and 150 mg/kg) reduced tumor volume, induced cell death, and modulated BAX/Bcl‐2 and Wnt/β‐catenin pathways in an in vivo analysis." (PMID 40964147, 2025). "This inhibition is accompanied by the modulation of pro- and anti-apoptotic proteins BAX and BCL-2, a reduction in MYCN mRNA expression, and a decrease in TNF-α secretion, suggesting a direct impact on tumor growth and cell survival." (PMID 40942095, 2025). "In double-hit lymphomas, combined dysregulation of MYC and BCL2 (often with BCL6) results in synergistic oncogenesis, characterized by rapid tumor growth and resistance to apoptosis." (PMID 41010038, 2025). "miR-34a exerts its anti-tumour effects by targeting the MET proto-oncogene and BCL2, key regulators of cancer progression." (PMID 40978098, 2025). "On this basis, we verified that exosomes derived from HUVECs and tumor cells containing LYPLAL1-DT were efficiently internalized by SCLC cells, leading to decreased miR-204-5p levels and increased PFN2 and BCL2 expression in the recipient tumor cells." (PMID 41551597, 2025). "This study defines novel molecular subtypes of HCC and reveals that HPX exerts anti-tumor effects through TNF-α-mediated mitochondrial apoptosis, characterized by an increased Bax/Bcl-2 ratio." (PMID 41008813, 2025). "The transformed tumor expressing CD10, BCL2, BCL6, and MYC with high Ki-67 (~70%) is consistent with double-expressor or double-hit DLBCL, associated with rapid proliferation and transformation from FL." (PMID 41146768, 2025). "The expression levels of MCM3, BCL2, and N-cadherin increased, whereas those of cyclin A, BAX, and E-cadherin decreased in ZMIZ2-overexpressing tumor tissues." (PMID 41502508, 2025). "Biologically, ASCL1 plays a crucial role in tumor initiation and maintenance by regulating MYCL, SOX2, RET, BCL2, and DLL3, all of which contribute to NE differentiation and tumor survival." (PMID 40333678, 2025). "When tumor cells develop resistance, they often activate other pathways such as RAS/RAF/MAPK and Apoptotic Blockade (BCL‐2/MCL‐1)." (PMID 41355397, 2025). "For example, IL-2-modified sEVs loaded with miRNAs directed against Bcl-2 and VEGF were able to improve immune responses and tumor suppression." (PMID 40688030, 2025). "Various BCL-2, BCL-xL, and MCL-1 inhibitors induce apoptosis in NB cells, and BCL-2 mRNA and protein levels are increased in ALKF1174L/MYCN NB tumours compared to tumours with only MYCN amplification." (PMID 41511287, 2025). "It has been found that the up-regulation of lncRNA NEAT1 can increase the expression of Bcl-2 and EGFR, thus promoting the proliferation and invasion of tumor cells." (PMID 41186893, 2025). "In CRC, the Bcl-2/BAX ratio has been identified as a crucial prognostic marker, correlating with tumor grade, stage, and size in patients." (PMID 41441038, 2025). "BCL2 and BCL-XL have been reported to be frequently overexpressed in senescent tumor cells to prevent their apoptotic clearance." (PMID 40940829, 2025). "In this study, expression levels of key apoptotic and survival-related genes, including Bax, Bcl-2, Caspase-3, c-MET, and HGF in response to TAS-115 and its combination with DOXO in 3D tumor spheroids." (PMID 41289612, 2025). "The study demonstrated that OMVs inhibited tumor growth in mice and significantly increased apoptosis in CT26 cells by upregulating Bax expression and downregulating Bcl-2, thereby reducing the Bcl-2/Bax ratio." (PMID 40236702, 2025). "WB analysis revealed that FAM84A knockdown led to a decrease in N-cadherin, C-myc, CDK6, and Bcl-2 levels, while E-cadherin and Bax expression increased, indicating that FAM84A plays a critical regulatory role in tumor cell growth, metastasis, and apoptosis." (PMID 41179292, 2025).
tumor (continued). "Immunohistochemistry showed CK7, EMA, BCL2, and CD99 positivity, paralleling some features of our case, though our tumor was biphasic with predominantly epithelial differentiation and neuroendocrine morphology." (PMID 41393681, 2025). "introduced a novel dual‐target inhibitor that disrupts the BCL‐2/BCL‐xL complex effectively, with PDX models confirming a 30–40% reduction in tumor growth." (PMID 39830019, 2025). "When tested in in vivo studies, the combination of CBD (5 mg/kg) and DOX reduced tumor volume (p < 0.001, n = 4), increased the expression of BAX and cleaved caspase-3, and decreased Bcl2 and mTOR." (PMID 40006844, 2025). "To elucidate the relationship between classical apoptosis and anoikis resistance, we examined the expression levels of key apoptosis markers (e.g., BAX, BCL2, CASP3) between tumor and normal tissues, as well as between the C1 and C2 subtypes." (PMID 40861804, 2025). "Tumor cells are commonly positive for CD10 (66% of cases), BCL2 (63% of cases), BCL6 (94% of cases), and MUM1 (100% of cases)." (PMID 39897193, 2025). "Its advantage lies in effectively inhibiting MYC and Bcl-2 mediated cell proliferation and anti-apoptotic signals, making it particularly suitable for DEL patients with high tumor burden (elevated LDH), as in the present case." (PMID 41229502, 2025). "Its selectivity for tumor cells and independence from MDR1 or BCL2 pathways highlight its therapeutic potential in apoptosis-resistant cancers." (PMID 40869364, 2025). "In vivo experiments confirmed that the co‐administration of IDET and paclitaxel significantly suppresses tumor growth in TNBC models, accompanied by a marked reduction in phosphorylated STAT3 and Bcl‐2 expression, while exhibiting favorable systemic tolerance." (PMID 40918170, 2025). "Oncogenes show specific activity in tumor cells, with LMO2, LYN, TNFRSF17, CARD11, and BCL7A being active in Tumor B1, while BCL2 and WAS are specifically active in Tumor B2." (PMID 41238550, 2025). "FL496-treated MPM cells resulted in strong inhibition of the expression of survivin, Mcl-1, Bcl-2, Bcl-XL, and the induction of active caspase-3, cleaved PARP, and PUMA, which were further confirmed using MPM tumor tissues via IHC analysis." (PMID 41121175, 2025). "FPHPE treatment markedly enhanced the cleavage of caspase‐3 and its downstream substrate PARP, while also elevating the Bax/Bcl‐2 ratio in both HCC cell lines and tumor tissues." (PMID 41200213, 2025). "Our Protein–protein interaction (PPI) network analysis results demonstrated that the key target genes of FSH for anti-tumor treatment were AKT1, EGFR, BCL2, CTNNB1 and HSP90AA1." (PMID 40230723, 2025). "In our case, the tumor was of monophasic histology and was diffusely positive for TLE1, Bcl2, and CD56 immunostaining." (PMID 40747128, 2025). "Additionally, inhibition of ACSLs may increase tumor cell sensitivity to venetoclax, a BCL2 inhibitor, since electron transport chain Complex I and II activity is positively correlated with resistance to venetoclax, and we observed that TriC decreased expression of subunits of Complexes I and IV." (PMID 39853696, 2025). "↑ Bax pro‐apoptotic protein → ↓ Bcl‐2, NF‐κB, and MMP‐9 → apoptosis induction and tumor growth inhibition." (PMID 40761486, 2025). "Co-cultures with CD40L-expressing stromal cells, mimicking the tumor microenvironment (TME), induced resistance to BCL2 and BCLXL targeting BH3-mimetics via cell-type specific upregulation of BCLXL or MCL1." (PMID 40819126, 2025).
tumor (continued). "The results showed that cyanidin inhibited the growth and migration of tumor cells by promoting apoptosis, ERG1, and cell growth phase (G1/M) suppression as well as by attenuating SEPW1, HIF2A, Bcl‐2, E‐cadherin, caspase‐3, and ROS production." (PMID 40321606, 2025). "To further validate tumor cell apoptosis, we performed western blot analyses showing upregulated cleaved caspase‐3 and BAX expression with concurrent BCL‐2 downregulation in treated spheroids." (PMID 40847445, 2025). "Immunohistochemical (IHC) studies of the bone trabeculae showed the intact structure, and the tumor cells exhibited strong diffuse positivity for CD20, CD79a, Pax-5, CD10, and BCL-2." (PMID 40746899, 2025). "NFκB enhances the expression of antiapoptotic genes like BCL2, CLIP, and cIAP and increases the survival of tumor cells." (PMID 38571491, 2024). "To further elucidate the relationship of AR and BCL2 expression, we studied CP336, a PDX with 2 tumor cell populations: AR-positive/BCL2-negative and AR-negative/BCL2-positive." (PMID 39286979, 2024). "Unlike previous studies, our TMA-trained model can predict the proportion of positive tumor cells in c-MYC- and BCL2-stained WSIs." (PMID 38243330, 2024). "Results from viability assays and measurements of BCL2 and caspase 3 in the H69V cell line suggest that KEAP1 silencing effectively affects the drug response, with contrasting effects on tumor cells when the two drugs were used separately." (PMID 38791966, 2024). "It binds to the BH3 domain of BCL2 with subsequent release of sequestered BH-3-only proteins, thereby triggering BAX/BAK-mediated rapid tumor-cell death and anti-tumor activity." (PMID 38421404, 2024). "It has been reported that the combined use of BCL2, CDK4/6 inhibitors or MEK inhibitors can synergistically enhance the anti-tumor effects of MDM2 inhibitors in different types of tumors." (PMID 39215364, 2024). "UPR sensors, such as ATF4, upregulate the expression of the antiapoptotic genes BCL-2 and FLIP and protect tumour cells against apoptosis in response to drug-induced stress, leading to tumour cell resistance to chemotherapeutic drugs." (PMID 38297380, 2024). "The tumor suppressor PTEN is downregulated, while the antiapoptotic component Bcl-2 is upregulated in response to activated PI3K/AKT signaling." (PMID 39524849, 2024). "Finger Citron inhibits tumor cell proliferation and invasion and induces apoptosis by downregulating Cyc-D1, MMP and bcl-2 through siRNA-mediated Zeb1 silencing replication to promote Zeb1 overexpression." (PMID 38817861, 2024). "Data illustrated that Bcl-2 SNA was efficiently taken up by tumor cells, escaped from endo/ lysosomes under light irradiation, and inhibited tumor growth by 95%, ultimately promoting cancer cell apoptosis." (PMID 38951806, 2024). "One tumor (case 19) in a 31-year-old female showed a double-hit genotype, which is defined by two chromosome translocations involving MYC and BCL2 and/or BCL6 rearrangements." (PMID 38730692, 2024). "Inhibit the proliferation of tumor cells and induce apoptosis; the levels of p-Akt, p-mTOR, p-MEK1/2, p-ERK1/2, Bcl-2 and Bcl-xL are down-regulated, and the level of cleaved-Caspase 3 is up-regulated." (PMID 39045282, 2024). "By editing the BCL-2 gene, CRISPR-Cas9 can disrupt its function, promoting apoptosis in cancer cells and potentially hindering tumor growth." (PMID 38195537, 2024). "Like BCL-2, the related myeloid cell leukemia (MCL)-1 protein exerts anti-apoptotic effects to protect tumor cells." (PMID 39272790, 2024). "CD45 indicates the lymphoid origin of the neoplasm, CD3 and CD8 are usually expressed in T-cell lymphomas, Bcl-2 expression is characteristic of extranodal lymphomas, and CD56 is an NK-cell molecular marker and is associated with epitheliotropism." (PMID 39583401, 2024).
tumor (continued). "The induction of anti-apoptotic proteins Bcl-2 and survivin, both of which are introduced by VEGF, also play a crucial role in tumor progression by protecting the neovasculature of tumors from apoptosis." (PMID 38339258, 2024). "Meanwhile, the delivered Cur successfully induced tumor cell apoptosis and activated ICD by inhibiting NF-κB phosphorylation and Bcl-2 protein expression and activating caspase and Bax apoptotic signaling." (PMID 39431008, 2024). "Pro-survival B-cell lymphoma-2 (BCL-2) family proteins BCL-2 and BCL-XL are the targets of anti-tumour drugs, but resistance is emerging." (PMID 38368459, 2024). "In the tumor sections from mice treated with BFC1108, we observed an exposure of the Bcl-2 BH3 domain." (PMID 38329389, 2024). "The relevance of prognostic biochemical, histological, and imaging parameters, such as IGF-2 levels, vimentin, CD34, bcl-2, or CD99 positivity but cytokeratin negativity, and tumor size > 10 cm, is unclear." (PMID 39138498, 2024). "Subsequent immunoblot analysis of resected tumor tissue showed that the LRP1 β∆‐chain exerted pro‐apoptotic effects by upregulating Bax and downregulating Bcl‐2 expression." (PMID 39405202, 2024). "In concordance, HACE1 suppressed the expression of CCND1, Bcl-2, and MMP2 in tumor tissue, with EHop-016 intensifying the inhibitory effects on these proteins." (PMID 38706891, 2024). "IHC was used to assess the expression of PCNA, BCL-2, and cleaved caspase-3 in tumor tissues, revealing decreased expression of PCNA and BCL-2 and increased expression of cleaved caspase-3." (PMID 38334883, 2024). "Immunohistochemical examination showed expression by the tumor cells of antibodies to CD20, CD5, Bcl2, and cyclin D1." (PMID 38698463, 2024). "Our results indicate that stromal FOXC1 and tumor pERK1‐2 expression provide stronger prognostic value compared to established factors, including cell of origin and MYC/BCL2 double expression." (PMID 39404228, 2024). "Analysis by ML models and methods confirmed the findings that the addition of both stromal FOXC1 and tumor pERK1‐2 to established factors of prognosis (NCCN‐IPI, cell of origin, and MYC/BCL2 double expression) improved C‐index." (PMID 39404228, 2024). "Other studies have shown that pediatric solid tumors are more dependent on BCL-XL and MCL-1 than BCL-2, and that the dual inhibition of BCL-XL and MCL-1 provides synergistic anti-tumor activity in EWS cell line cultures." (PMID 39199601, 2024). "The results indicated that the expression levels of the genes BCL2 and EGFR were significantly (p < 0.001) higher in normal tissue than in tumor tissue." (PMID 39202273, 2024). "Multivariate backward linear regression with adjustment for all studied variables showed that age, sex, tumor site, tumor size, TIL count, and BCL2 score were independent variables affecting GATA3 expression." (PMID 38668712, 2024). "There is strong evidence that the interaction between cancer-specific Bcl-2, STAT3/NF-κB signaling and the recruitment of M2-TAM promote a pro-tumor microenvironment." (PMID 39061137, 2024). "The levels of pro-apoptotic proteins Bax and Cleaved Caspase3 in tumor tissues were significantly increased following L.p CMU-Pb-L5 intervention, while the expression level of the anti-apoptotic protein Bcl-2 was significantly decreased." (PMID 39439459, 2024). "The expression of HMGN1, HSP90AA1, BCL2, and AGER was verified in TCGA and GTEx databases, and HMGN1, HSP90AA1 and AGER were found to be highly expressed in tumor tissues." (PMID 38713284, 2024). "Senescent cells harbour vulnerabilities allowing their specific killing by various ‘senolytics’, including BCL‐2 and BCL‐xL inhibitors (venetoclax, navitoclax, A1331852...) that were observed to augment the tumour response to CDK4/6i." (PMID 36453028, 2024). "Expression of PTPRO was negatively correlated with p-JAK2, p-STAT3, Bcl-2, and Snail levels in LUAD tumor samples." (PMID 38182570, 2024).